HDHD2 (haloacid dehalogenase like hydrolase domain containing 2)
Synonyms: DKFZP564D1378; 3110052N05Rik; HEL-S-301
Tractability: Small molecule: it has a binding pocket of medium quality. PROTAC: ubiquitination databases record sites on it; its protein half-life has been measured.
Gene: Protein-coding gene on chromosome 18 (47,076,104 to 47,151,106, reverse strand). Ensembl gene ENSG00000167220.
Subcellular location (Human Protein Atlas): Vesicles
Gene Ontology:
Molecular function: enzyme binding; protein binding; phosphatase activity
Cellular component: extracellular exosome
Genetic constraint (gnomAD): Loss-of-function variants: 17 observed, 15.04 expected, observed/expected ratio (o/e) 1.13, 90% interval 0.77 to 1.67. The upper end of that interval is the gene's LOEUF score, 1.67, which puts it in group 6 of 6, group 1 being the genes least tolerant of losing a copy. Missense variants: 222 observed, 248.71 expected, observed/expected ratio (o/e) 0.89, 90% interval 0.8 to 1. Synonymous variants: 103 observed, 95.36 expected, observed/expected ratio (o/e) 1.08, 90% interval 0.92 to 1.27.
Homologues: Orthologues: chimpanzee HDHD2 (99% identical), macaque HDHD2 (98% identical), dog HDHD2 (95% identical), pig HDHD2 (94% identical), guinea pig HDHD2 (93% identical), mouse Hdhd2 (89% identical), rat Ier3ip1 (81% identical), tropical clawed frog hdhd2 (79% identical), zebrafish hdhd2 (78% identical), rabbit HDHD2 (76% identical), Caenorhabditis elegans K08B12.3 (51% identical), Drosophila melanogaster CG17294 (49% identical). Paralogues in human: LHPP (44% identical), PGP (30% identical), PDXP (29% identical).
Diseases named in the same sentence as HDHD2 in open-access papers:
HDHD2 is named in the same sentence as 2 diseases in open-access papers, as found by Europe PMC text mining. Sharing a sentence is not in itself a finding about the gene and the disease. The quoted sentences say what the papers report.
myocardial infarction (1 paper, 2024). Gross necrosis of the myocardium, as a result of interruption of the blood supply to the area, as in coronary thrombosis. "The Role of HDHD2 in Myocardial Infarction: HDHD2 was identified as a novel therapeutic target in MI in our study." (PMID 39715222, 2024). "Following co-localization analysis for myocardial infarction (MI), we focused on four potentially relevant genes: DPEP1, CD8A, CD30 Ligand, and HDHD2." (PMID 39715222, 2024).
HDHD2 also shares sentences with these, for which no sentence is quoted: Hypertension (1 paper).